EGFR (epidermal growth factor receptor)
Diseases named in the same sentence as EGFR in open-access papers (continued):
Sharing a sentence is not in itself a finding about the gene and the disease.
pancreatic cancer (continued). "Inhibition of the epidermal growth factor receptor (EGFR) by erlotinib or cetuximab has limited or no activity, respectively, in pancreatic cancer." (PMID 22367239, 2013). "Our experiments also showed that HDACi Panobinostat (PS) reduced EGFR and c-Met expression in pancreatic cancer cells (data not shown)." (PMID 23922886, 2013). "In the present study in human pancreatic carcinoma cell line PANC-1, Δ6D expression was tested for responsiveness to the synthetic PPARδ agonist GW0742, under either MEK/ERK1/2 or epidermal growth factor receptor (EGFR) signaling pathway blockade." (PMID 24294133, 2013). "Moreover, in breast cancer cells, survivin expression has been reported to be regulated by EGFR via the PI3K/AKT pathway, another important pathway in pancreatic cancers." (PMID 22723871, 2012). "Many oncogenic molecular pathways including EGF/EGFR, Ras-Raf-MEK, PI3K/Akt, JAK/STAT, p16INK4A/retinoblastoma, Smad4/TGF-β, and hedgehog signaling pathways, have been reported to be involved in the pathogenesis of pancreatic cancer." (PMID 22348037, 2012). "However, in melanoma and pancreatic cancer, HER3 appears to be a preferred dimerization partner of EGFR." (PMID 23198146, 2012). "Inhibition of EGFR signaling by treatment with cetuximab in combination with adjuvant therapy seemed a promising approach for pancreatic cancer treatment in phase II clinical trials, but showed no benefit over standard treatment in phase III trials." (PMID 24213498, 2012). "As expected, baseline levels of pancreatic cancer cell EGFR protein did not correlate with the extent of erlotinib-induced growth inhibition." (PMID 21792199, 2011). "In search of the mechanisms that promote tumourigenic ErbB signalling, we have previously demonstrated that unlike NSCLC, pancreatic cancer cells lack activating EGFR mutations." (PMID 21792199, 2011). "We conclude that stromal CAF-secreted NRG-1 stimulates ErbB3/AKT signalling and promotes pancreatic cancer cell tumourigenesis, providing a mechanism that may contribute to PDAC resistance to anti-EGFR therapy." (PMID 21792199, 2011). "In the pancreatic cancer cell line Panc-1, DNA synthesis induced by neurotensin was independent of EGFR transactivation, whereas in the prostate cancer cell line PC-3, neurotensin stimulated mitogenesis by a PKC-dependent transactivation of EGFR." (PMID 21961726, 2011). "Collectively, these data indicate that ΔNp63α binds and trans-activates the EGFR and 14-3-3σ promoters in pancreatic cancer cells and that these actions of ΔNp63α do not necessarily occur in other cell types." (PMID 22053213, 2011). "Despite the advances in chemotherapy, particularly gemcitabine, and the development of new tyrosine kinase inhibitors, such as erlotinib (Tarceva) an epidermal growth factor receptor (EGFR) inhibitor, the prognosis for patients with pancreatic cancer is dismal." (PMID 21470434, 2011). "Altered expression or constitutive activation of the epidermal growth factor receptor (EGFR/HER1/erbB1) commonly occurs in both primary and metastatic pancreatic cancers and is often a critical component in progressive growth and resistance to normal mechanisms of cell death." (PMID 16622465, 2006). "Therefore, the present data suggests that for this pancreatic cancer cohort, EGFR, ERK1, ERK2, c-Jun, and c-Fos transcript levels are not gender-dependent." (PMID 40305202, 2025). "However, TMEM16A modifies the pattern of EGF-induced phosphorylation of EGFR without affecting Akt or Erk phosphorylation in pancreatic cancer." (PMID 37309001, 2023). "Moreover, kaempferol sensitizing pancreatic cancer to Erlotinib treatment may probably be related to the PI3K/AKT signaling pathway and Epidermal growth factor receptor (EGFR), a transmembrane protein involved in TKI resistance." (PMID 37239974, 2023).
pancreatic cancer (continued). "An in vitro study of a tetravalent recombinant EGFR bispecific (rEGFRbi) antibody targeting wild-type (wt) EGFR showed similar efficacy to other platforms, and a previous small phase 1 trial in pancreatic cancer showed durable responses in patients with no dose-limiting toxicities." (PMID 37754534, 2023). "Additionally, one study showed that NETs could induce pancreatic cancer cells migration, invasion and EMT through activating the IL-1β/epidermal growth factor receptor (EGFR)/extracellular signal−regulated kinase (ERK) pathway." (PMID 36993957, 2023). "On the other hand, DYRK1A was highly expressed in lung and pancreatic cancer cells, and that its protein level was positively correlated with that of STAT3, c-MET and EGFR as it was found that DYRK1A siRNA could suppress the levels of EGFR and MET receptor tyrosine kinases." (PMID 36012629, 2022). "Therefore, this study has completed the construction of dual-recognition specific antibodies (anti-EGFR antibody for pancreatic cancer cells and anti-FAP for fibroblasts surrounding pancreatic cancer cells), which remove the Fc fragment and preserve the specific target region, Fv fragments." (PMID 35745775, 2022). "Thus, some argue that EGFR is overexpressed in pancreatic cancers, independently from histopathological features without predicting survival." (PMID 35448172, 2022). "To investigate whether MYEOV acts as ceRNA to exert certain regulatory effects on genes such as GPRC5A, SERPINB5, KRAS, EGFR, EIF4G2, and PDCD4, we analyzed the differential expression of these genes in pancreatic cancer and normal pancreatic tissues by the GEPIA database." (PMID 36358856, 2022). "In a study on pancreatic cancer, the upregulation of PGM3 correlated significantly with gemcitabine resistance, while inhibiting PGM3 significantly suppressed the malignant phenotype of tumor cells and enhance the drug sensitivity of gemcitabine by modulating the EGFR-Akt pathway." (PMID 36275679, 2022). "Furthermore, lower expression levels of p-EGFR, p-PI3K and p-AKT were observed when combined with Rg3, which revealed that Rg3 downregulates expressions of p-EGFR, p-PI3K, and p-AKT, thereby sensitizing pancreatic cancer cells to erlotinib." (PMID 34975466, 2021). "A similar analysis using bulk RNA-seq of pancreatic cancer patients and non-cancer patients revealed that of the 41 ligands that are upregulated in cancerous tissues, four activate or modulate EGFR, including the EGFR ligand TGF-α, and modulators CEACAM1, FGF1, and TFF1." (PMID 34054523, 2021). "Importantly, licochalcone A–mediated survivin down‐regulation is partly dependent on the suppression of EGFR downstream Akt and ERK1/2 signallings, which is consistent with the previous report that reduces survivin protein by brexpiprazole overcomes EGFR TKI resistance in lung and pancreatic cancer." (PMID 33247550, 2021). "However, afatinib did not change PD-L1 expression in pancreatic cancer cell lines, suggesting that EGFR is not the main factor responsible for immunosuppression in pancreatic cancer." (PMID 34503236, 2021). "Furthermore, in pancreatic cancer, COX-2 can promote angiogenesis in the EGFR/p38-dependent manner, while in chronic obstructive pulmonary disease, MSC-induced airway inflammation and emphysema are partially mediated by silencing COX-2 via the p38 and ERK pathways." (PMID 33833129, 2021). "However, whether EGFR pathway and HSF1 interact in pancreatic cancer and their “boss-subordinate relationship” remains unclear." (PMID 33422093, 2021). "However, we were unable to detect MIG-6, which has been reported to be responsible for NDRG1-mediated EGFR downregulation in pancreatic carcinoma cell lines (data not shown), which illustrates the need for further study of the means of action." (PMID 35008802, 2021). "Furthermore, silencing PODXL in pancreatic cancer cells resulted in the down-regulation of EGFR, but not vice versa." (PMID 32587323, 2020).
pancreatic cancer (continued). "Erlotinib, a small molecule tyrosine kinase inhibitor of the epidermal growth factor receptor (EGFR) pathway, is the only non-cytotoxic agent approved for the treatment of pancreatic cancer; however, it is seldom utilized due to its marginal benefit in this disease." (PMID 31338636, 2020). "In this study, we provide a novel notion that PRMT5 induces the phosphorylation of EGFR, and then activates phosphorylation of Akt and its downstream GSK3β, and thereby up‐regulates expression of β‐catenin to enhance the migratory and invasive motility and promotes EMT of pancreatic cancer cells." (PMID 31851779, 2020). "Here, the authors establish a KRAS-driven mouse model of pancreatic cancer with conditional loss of AGO2 and show that the early phase of neoplastic lesion initiation is dependent on EGFR/RAS but not AGO2, while AGO2 is required for pancreatic ductal adenocarcinoma progression and metastasis." (PMID 32499547, 2020). "Treatment of mice xenografted with human pancreatic cancer with A platensis led to an underexpression of endothelin 1, pentraxin 3 and acidic fibroblast growth factor and an overexpression of 3 angiogenic proteins in tumours, including VEGF‐A and AREG acting via VEGFR or EGFR." (PMID 31957261, 2020). "The results from both in vitro and in vivo experiments suggested that DTLL enhanced DNA damage via EGFR/HER2‐dependent blockage of PI3K/AKT/mTOR and PD‐L1 signaling pathways in cancer cells, leading to the inhibition of cell proliferation and immunosurveillance escape from pancreatic tumor." (PMID 30681288, 2019). "To explore whether VPA might show any therapeutic effect on pancreatic cancer, we investigated its anti-proliferative/anti-survival activities in the EGFR/ErbB2/ErbB3-coexpressing (HPAF-II, MPanc96) and ErbB3-negative (MiaPaca-2, Panc-1) pancreatic cancer cell lines." (PMID 30961642, 2019). "Among all subfamilies of RTKs, the ErbB family members consisting of the epidermal growth factor receptor EGFR (ErbB1), HER2 (ErbB2), HER3 (ErbB3), and HER4 (ErbB4) play important role in the initiation and maintenance of a variety of human cancers, including pancreatic cancer." (PMID 30961642, 2019). "After demonstrating the EGFR/HER2‐mediated bispecificity of DTLP in pancreatic cancer cells, we used DTLP and AE (the chromophore of LDM) to produce DTLL and test whether DTLL exhibited potent antineoplastic bioactivity for pancreatic cancer therapy." (PMID 30681288, 2019). "The abnormal overexpression or activation of AKT has been observed in cancers including lung, ovarian and pancreatic cancers, and AKT could be activated by epidermal growth factor receptor (EGFR), implying that targeting EGFR or AKT could offer important approaches for cancer prevention and therapy." (PMID 31696057, 2019). "Previous reports indicated that EGFR phosphorylation is one of the most common events in pancreatic cancer progression, and we discovered that EGFR phosphorylation was downregulated in periostin-shRNA lentivirus-transfected SW1990 and BxPC-3 cells, whereas the total amount of EGFR was unchanged." (PMID 29163770, 2017). "Third, we did not measure EGFR expression levels in pancreatic cancer tissues or plasma." (PMID 27596051, 2016). "Therefore, to understand the migratory inhibition signaling pathways of kaempferol treatment in human pancreatic cancer cells, we examined the phosphoylation level of EGFR, Src, AKT, and ERK1/2 after subjecting pancreatic cancer cells to time-dependent kaempferol treatments." (PMID 27175782, 2016). "However, in pancreatic carcinoma cells, EFEMP1 could bind to EGFR and contribute to the enhancement of tumor growth via AKT and MAPK signaling pathway." (PMID 27351229, 2016). "Hence, the change in the total level of EGFR and HER2 in response to canertinib and afatinib treatment, predicts a possible inactivation of HER3 and disabling of HER4 mediated signaling events such as proliferation and apoptosis in pancreatic cancer cells." (PMID 25686822, 2015).
pancreatic cancer (continued). "Thus, we concluded that the up-regulated EGFR pathway and facilitation of tumorigenesis by miR-1178 may be due to decreased CHIP expression in pancreatic cancer cells." (PMID 25635996, 2015). "Thus, we speculated that the ectopic activation of the EGFR/AKT/p21 and EGFR/SRC/E-cadherin pathways might partially account for the effects of miR-1178 in pancreatic cancer cells." (PMID 25635996, 2015). "While multiple reports have described the constitutively active oncogenic KRAS to be independent of EGFR, recent evidence in pancreatic cancer has indicated that signaling by mutant KRAS may be dependent on upstream activation proposed of EGFR." (PMID 25992771, 2015). "In the current study, we tested this hypothesis, investigating the impact of concurrent inhibition of IGF-IRs and epidermal growth factor receptors (EGFR/Her-2) by NVP-AEW541 and lapatinib tyrosine kinase inhibitors, respectively, on pancreatic cancer cell lines and particularly on PCSCs." (PMID 25886138, 2015). "Additionally, the MUC4 protein expression was not inhibited by erlotinib, a reversible EGFR inhibitor, in pancreatic cancer cells." (PMID 25686822, 2015). "One of the probable explanations for the lack of a meaningful benefit from anti-EGFR TKIs in pancreatic cancer could be the development of acquired resistance to these agents, which is a mechanism well studied in lung cancer." (PMID 25935754, 2015). "In pancreatic cancer, silencing of galectin-3 has shown to enhance the cell surface interaction between MUC1 and EGFR in the absence of EGF stimulation and reduced the rate of endocytosis of MUC1-EGFR complex which leads to the noticeable cell surface localization of MUC1." (PMID 25261375, 2014). "This could be a significant benefit to the treatment of patients, particularly those with pancreatic cancer with EGFR-dependent phenotypes, but no known biomarkers of EGFR inhibitor response." (PMID 22045191, 2012). "However, we determined that ΔNp63α is a transcriptional activator of EGFR in pancreatic cancer cells, but not in HEK293 or H1299 cells." (PMID 22053213, 2011). "AsPC-1 pancreatic cancer cell murine subcutaneous xenografts were developed in the presence and absence of CAF and were subsequently treated with epidermal growth factor receptor (EGFR) inhibitors (erlotinib) and ErbB3 inhibitors (MM-121, monoclonal ErbB3 antibody)." (PMID 21792199, 2011). "Hence, we aimed to investigate the relative expression of NTR1 and EGFR of BxPC-3, PANC-1 and MIA PaCa-2 pancreatic cancer cells in dependence of cell density and extracellular pH (pHe), representing conditions in tumor aggregates with declining vascular support." (PMID 24212612, 2011). "Similarly, carcinogen-induced pancreatic cancer in the hamster and rat expressed only TGFα and EGFR, but not EGF." (PMID 16822304, 2006). "The PARC study is an open, randomized controlled trial investigating the survival of patients with primary non-metastatic locally advanced pancreatic cancer after trimodal therapy with gemcitabine-based chemoradiation and EGFR-targeting therapy with the monoclonal antibody cetuximab." (PMID 16219105, 2005). "Moreover, molecular profile analysis of patients from the randomized phase III AIO-PK0104 study of gemcitabine with or without erlotinib in pancreatic cancer did not demonstrate a correlation between EGFR amplification (18%) or EGFR overexpression (46%) with benefit from erlotinib." (PMID 40507311, 2025).
pancreatic cancer (continued). "While preclinical efficacy from afatinib in pancreatic cancer has been suggested to correlate with EGFR/HER2/HER3 expression and occurred irrespective of KRAS status, disease stabilizations seen in KRASMUT tumors in our study may have been solely due to capecitabine chemotherapy." (PMID 40507311, 2025). "Hence, we hypothesized that the abnormal activation EGFR and its downstream pathways may induce PTSs in pancreatic acinar cells and the accumulation/activation of HSF1 in pancreatic cancer tumorigenesis may be a passive response of the cells against to increasing PTSs." (PMID 33422093, 2021). "Furthermore, the EGFR signaling is required to initiate the KRAS oncogene-driven PanIN lesions and PDAC, and may be the possible reason that erlotinib exerts therapeutic effects for patients with pancreatic cancer." (PMID 34360896, 2021). "Interestingly, in a pancreatic cancer patient, no residual EGFR activity could be inferred by INKA in a tumor biopsy after erlotinib treatment." (PMID 30979792, 2019). "In addition to TGFβ and KRAS activation, epidermal growth factor receptor (EGFR) signaling, a cascade aberrantly activated in the majority of PDACs, has been demonstrated to play a critical role in HH/GLI1-regulated tumor-initiating pancreatic cancer cells (Eberlet al., 2012)." (PMID 25352983, 2014). "The results suggested that there was a positive correlation between Hub-EGFR.Sig and MSI in most cancer types but a negative correlation in adrenocortical carcinoma and pancreatic cancer." (PMID 40574864, 2025). "For example, in pancreatic cancer, the ITGB1-driven Src-AKT pathway, which is independent of EGFR signaling, enhances resistance to cetuximab therapy." (PMID 40685383, 2025). "Epidermal growth factor receptor (EGFR) signaling pathway defects and oxidation of specific translational regulatory proteins were observed in pancreatic cancer cells in the absence of Nrf2." (PMID 39286246, 2024). "The first EGFR-targeting TKI, gefitinib, was approved in 2003 for non-small cell lung cancer (NSCLC), followed by erlotinib for NSCLC and pancreatic cancer in 2004 and 2005, respectively." (PMID 39065587, 2024). "Proteomic analysis reveals the selective enrichment of known exosome markers and also signaling proteins involved in pancreatic cancer progression (KRAS, CD44, and EGFR) in oncogenic exosomes compared to exosomes from non-malignant cells." (PMID 32974169, 2020). "Unlike EGFR mAb cetuximab, even though EGFR TKI erlotinib is approved to treat pancreatic cancer, negligible improvement in a group of responsive population was observed." (PMID 30449278, 2018). "The assay also showed that KAN0439834 did not dephosphorylate EGFR and IGF-1R, kinases which are overexpressed in pancreatic carcinoma cells." (PMID 29856777, 2018). "Further, EGFR knockdown showed that pSTAT3 levels were lower in EGFR-shRNA pancreatic cancer cells compared to NTC-shRNA control cells without altering total protein levels, suggesting that STAT3 phosphorylation is partly dependent on EGFR protein levels." (PMID 29262554, 2017). "425(scFv)-ETA was strongly cytotoxic towards metastatic pancreatic cancer cells with an IC50 of less than 10 ng/mL, while EGFR-negative cells were unaffected at concentrations of immunotoxin lower than 10 μg/mL." (PMID 27153091, 2016). "Furthermore, high HAb18G/CD147 expression was significantly correlated with high EGFR expression (Spearman r = 0.3086, P = 0.0016), suggesting that the high expression levels of both HAb18G/CD147 and EGFR might have important roles in promoting pancreatic cancer progression." (PMID 27556697, 2016). "In contrast, there were no changes in the expression of EGFR and HER4 in both HER2 knockdown pancreatic cancer cells." (PMID 26035354, 2015). "As in pancreatic cancer, HER3 dimerized with EGFR and siRNA-mediated inhibition of HER3 expression showed acquired resistance to erlotinib, suggesting that lack of HER3 expression makes these cells less dependent on EGFR." (PMID 37947595, 2023).